ADAM17 (ADAM metallopeptidase domain 17)
Diseases named in the same sentence as ADAM17 in open-access papers (continued):
Sharing a sentence is not in itself a finding about the gene and the disease.
infection (continued). "In our assay, control donor or ADAM17-depleted HaCaT cells were incubated with HPV16 PsVs for 1 hr, intensively washed to remove unbound virus, placed above recipient cells, and the next day assayed for infection." (PMID 31107240, 2019). "Interesting is that either conditional ADAM17 knockout mice or hematopoietic chimeric mice that lacked ADAM17 in leukocytes demonstrated accelerated neutrophil recruitment at sites of sterile inflammation as well as infection." (PMID 28487846, 2017). "While the airway expression of most SARS‐CoV‐2 entry factors may be lower, it is also interesting to focus on those proteins that remained unchanged between COPD and controls, including Furin, CTSL, ADAM17, and ITGA5, as these factors could still facilitate infection." (PMID 41047996, 2025). "Several transmembrane proteases, including ADAM17, transmembrane serine protease 2 (TMPRSS), and tumor necrosis factor (TNF)-converting enzyme, along with proteins like vimentin and clathrin are believed to play roles in the comprehensive process of establishing infection." (PMID 38339115, 2024). "Thus, besides junctional and adhesion molecule shedding, increased cell survival upon ADAM17 inhibition may explain enhanced adhesion and subsequently enhanced transepithelial migration of THP-1 cells during infection by P. aeruginosa." (PMID 35892600, 2022). "However, the activity of ADAM17 was not changed upon infection with S. pneumoniae in comparison to non-stimulated cells." (PMID 35892600, 2022). "Therefore, we propose that CD9 might regulate the local distribution of the protease ADAM17 and its EGFR-activating substrates, which then influences the organization of the HPV16 entry receptor platform and eventually infection." (PMID 32385608, 2020). "Infection was not further supported by the addition of GFs if the cells were treated with control siRNA in full medium (containing FCS) but was supported in ADAM17-depleted cells." (PMID 31107240, 2019). "However, there were significant increases in the amount of shed MUC1 following knockdown of MMP-14 at 8 but not 24 h of infection, although no changes were seen following knockdown of ADAM17." (PMID 19816567, 2009). "Therefore, to identify the target genes of ADAM17 in regulating effector CD8+ T cells, we performed proteomic analysis of enriched membrane proteins extracted from WT and ADAM17 KO CD8+ T cells isolated from recipient mice 7 days after LM-OVA infection in the co-transfer model." (PMID 38918390, 2024). "Therefore, we hypothesized that the functional impact of ADAM17 may not be limited to leukocytes and endothelial cells but could be also essential for epithelial cell functions during infection." (PMID 35892600, 2022). "Indeed, the fact that TMPRSS2, but not ADAM17 expression was downregulated upon infection might indicate the prominent role of TMPRSS2 in the context of SARS-CoV-2 infection." (PMID 34578296, 2021). "The beneficial effect on infection rates was observed when the cells were grown under starvation conditions (in medium without FCS) in the presence and in the absence of ADAM17." (PMID 31107240, 2019). "The absence of ADAM17 completely eliminated BVDV permissiveness in CRIB-1 cells, a BVDV-resistant MDBK clone, underscoring ADAM17’s critical role as an attachment factor in the pestiviral infection cycle." (PMID 39772144, 2024). "Consistent with the lack of expression of ADAM17 and therefore the inability of D1(A12) to change TNFR2 expression on Merlin-infected cells, blocking of ADAM17 did not significantly alter TNFα-induced cytokine production following infection with Merlin." (PMID 37561786, 2023). "This indicates that ADAM17 is not a host determinant of CSFV infection, and the infection process might require the involvement of other proteins." (PMID 38041163, 2023).
infection (continued). "With respect to viral infection ADAM17 facilitated the entry of the human papillomaviruses (HPV), and led to downregulation of CD16 on natural killer (NK) cells during chronic hepatitis C virus (HCV) infection resulting in a lack of infection eradication." (PMID 33392273, 2020). "We found that the levels of ADAM17, not ADAM15 or ADAM19, increased significantly upon infection." (PMID 30687645, 2018).
cardiovascular diseases (15 papers, 2016 to 2024). "Several chronic diseases, such as chronic inflammatory and cardiovascular disease, are associated with increased ADAM-17 activity." (PMID 38892098, 2024). "Loss of membrane ACE2 and a corresponding increase in plasma ACE2 are associated with worsened cardiovascular disease outcomes, a mechanism attributed to a disintegrin and metalloproteinase (ADAM17)." (PMID 38077924, 2023). "In summary, several lines of evidence support that low expression levels of the ACE2 membrane form (mACE2) and higher ADAM17 activity would be associated with cardiovascular disease." (PMID 33117379, 2020). "Additionally, several Dox_H3K27ac-upregulated genes including Egr-1, Adam17, Dusp6, Ddit4 and Angptl4 might potentially contribute to Dox-induced cardiotoxicity, since they have been proved to be associated with the progression of cardiovascular disease." (PMID 39014511, 2024). "Many studies have shown that ADAM17 can participate in the regulation of the occurrence and development of tumors, inflammatory diseases, nervous system, and cardiovascular diseases." (PMID 34035876, 2021). "A disintegrin and metalloproteinase 17 (ADAM17), also known as tumor necrosis factor-α-converting enzyme (TACE), promotes cardiovascular remodeling that plays a crucial role in cardiovascular diseases." (PMID 30046277, 2018). "There has been substantial progress in understanding how ADAM17 mediates a range of physiological functions and how ADAM17 mediates signaling pathway contributing to the pathological processes in a variety of neurological and cardiovascular disorders." (PMID 27803674, 2016). "Despite a plethora of data in various fields, the role of ADAM17 in the central regulation of cardiovascular modulation and related cardiovascular diseases is far from being elucidated." (PMID 27803674, 2016). "The extracellular structural domain of ADAM17 sheds to mediate cardiovascular disease." (PMID 37046278, 2023). "ACE2, ADAM17, and B1R are expressed on neurons within brain nuclei, including the hypothalamus and have been shown to be involved in regulating inflammation and autonomic function during the development of various cardiovascular diseases." (PMID 33375653, 2020). "Finally, we also discuss the contribution of ADAM17 as a potential therapeutic target in cardiovascular disorder and the neurogenic component of these cardiovascular diseases." (PMID 27803674, 2016). "Although there has been slow progress in translating the knowledge of ADAM17 into possible new treatments, because of the diversity of its substrates, it remains that ADAM17 could be used as potential novel target for the treatment of cardiovascular diseases." (PMID 27803674, 2016).
kidney disease (12 papers, 2012 to 2023). "Loss of TIMP3, the only known physiological inhibitors of ADAM17, is associated with age-related renal fibrosis and tubulointerstitial fibrosis, which are important prognostic marker in a wide variety of kidney diseases." (PMID 23401241, 2013). "Studies focusing on ADAM17 in kidney biopsies from patients with CKD and in experimental mouse models of renal disease suggest the importance of ADAM17 in kidney inflammation, fibrosis, and disease progression." (PMID 37108478, 2023). "Among the EGFR ligands, HB-EGF and TGF-α are released by ADAM17 and have a role in renal diseases." (PMID 26064952, 2015). "Interestingly, renal ADAM-17 is up-regulated in Ang II-induced kidney injury, and de novo expression occurs in human kidney disease, in proximal tubule, podocytes, and mesangial cells." (PMID 22629438, 2012). "Although ADAM10 and ADAM17 are clearly involved in both CKD and CVD, yet are more elaborately studied in the context of CVD, the role of ADAMs in the progression of renal disease and especially their role in cardiorenal disease is thus far a rather understudied field of research." (PMID 37108478, 2023). "We recently conditionally inactivated ADAM17 in podocytes and then determined how specific lack of ADAM17 affects the progression of kidney disease induced by STZ treatment." (PMID 34181080, 2021). "Since ADAM17 cleaves ACE2, the increases in ADAM17 expression and activity that occurs in kidney disease of all etiologies could partly account for the increases in circulating ACE2 and a higher risk for cardiovascular events." (PMID 34950686, 2021).
neurodegenerative disease (9 papers, 2016 to 2025). A disorder of the central nervous system characterized by gradual and progressive loss of neural tissue and neurologic function. "Given the pivotal role of ADAM17 in chronic inflammation, ADAM17 appears to be an attractive treatment target to delay or prevent low-grade chronic neuroinflammation and is associated with the pathophysiology of a number of neurodegenerative diseases." (PMID 38963109, 2024). "In this review, we will focus on the physiological and pathological functions of ADAM17 that have been characterized in vivo, particularly in the context of metabolic and neurodegenerative diseases." (PMID 38963109, 2024). "Animal model studies have further elucidated ADAM17's role in neurodegenerative diseases, showcasing its intricate interplay within the CNS." (PMID 38963109, 2024). "Alterations in ACE2 gene and protein expression, and activity mediated by A Disintegrin And Metalloprotease 17 (ADAM17), a member of the “A Disintegrin And Metalloprotease” (ADAM) family are implicated in several cardiovascular and neurodegenerative diseases." (PMID 33375653, 2020). "Given its crucial role in orchestrating APP shedding and TNF-α responses, it is reasonable to speculate that ADAM17 may exert dual and opposing effects on the development of neurodegenerative diseases." (PMID 38963109, 2024). "The role of vascular ADAM17 in neurodegenerative diseases remains poorly understood." (PMID 36937050, 2023). "Similarly, in neurodegenerative diseases such as AD and PD, activating the JAK/STAT pathway by ADAM17-mediated shedding of cytokine receptors contributes to neuroinflammation and neuronal dysfunction." (PMID 38963109, 2024). "A study exploring the impact of ADAM17 knockout in astrocytes showed an amelioration of HIV-1 Tat-induced inflammatory responses and neuronal death, suggesting the enzyme's involvement in neuroinflammatory pathways relevant to neurodegenerative diseases." (PMID 38963109, 2024).
inflammation (8 papers, 2011 to 2025). Aberrant reaction of the microcirculation characterized by movement of fluid and leukocytes from the blood into extravascular tissues. "These animals are viable and we show here that a deficiency of leukocyte-expressed ADAM17 markedly alters neutrophil infiltration into the lung with an overall diminution in their recruitment to the alveolar compartment during acute lung inflammation." (PMID 21603616, 2011). "In conclusion, this study shows that tissue-specific Adam17 deletion protects against renal inflammation and fibrosis." (PMID 34073747, 2021). "Our results reveal that in the context of lung inflammation, ADAM17 participates in the shedding of IL-6R, but in contrast to TNF-α and L-selectin, ADAM17 is not the primary sheddase of leukocyte IL-6R." (PMID 21603616, 2011). "Using conditional ADAM17 knock-out mice, we investigated leukocyte ADAM17 in acute lung inflammation." (PMID 21603616, 2011). "In conclusion, our study demonstrates for the first time that leukocyte ADAM17 regulates acute lung inflammation by modulating intra-alveolar neutrophil levels and the shedding of IL-6R, L-selectin, and TNF-α." (PMID 21603616, 2011). "Arndt and colleagues investigated the role of leukocyte-associated ADAM17 in acute lung inflammation by using a conditional knock-out mouse lacking ADAM17 in hematopoietic cells and their progenitors." (PMID 33579029, 2021). "Activated lung macrophages have also been shown to enhance IL6 trans-signaling via ADAM-17 leading to fibroblast proliferation and ECM deposition, and inhibition of sIL6Rα can attenuate pulmonary inflammation and fibrosis." (PMID 32210969, 2020). "Taken together, the results above suggest that ADAM17 is the primary sheddase of L-selectin and TNF-α by alveolar leukocytes, but not of the IL-6R during acute pulmonary inflammation." (PMID 21603616, 2011).
bacterial infection (6 papers, 2011 to 2024). "Collectively, our results suggest that the short-term benefit of ADAM17 inhibition might lead to enhanced secretion of IFNγ, while long-term inhibition of ADAM17 might be detrimental and could increase the risk of bacterial infection due to drastic decrease in soluble TNFα." (PMID 26683521, 2015). "Several studies reported induction of ADAM17 and its anti-inflammatory effect during bacterial infection." (PMID 27381289, 2016). "Specifically, our study has shown that bacterial infection of hBMECs is able to induce a ligand-dependent transactivation of EGFR, which requires the ADAM17-mediated cleavage and release of HB-EGF." (PMID 30687645, 2018).
metabolic disease (4 papers, 2017 to 2024). A congenital disorder (due to inherited enzyme abnormality) or acquired (due to failure of a metabolically important organ) disorder resulting from an abnormal metabolic process. "One promising regulator protein that has shown potential in modulating ADAM17 activity in metabolic diseases is iRhom2." (PMID 38963109, 2024). "This is explained by effects of TIMP3 on multiple proteases and receptors, suggesting that its metabolic effects are only in part due to ADAM17 inhibition and posing TIMP3 reconstitution at a more advanced stage as an approach against metabolic diseases compared to ADAM17 inhibition." (PMID 28751722, 2017).
heart disease (3 papers, 2013 to 2026). "Furthermore, two human iRhom1 variants associated with cardiac disease localize adjacent to the sterol-binding pocket and disrupt ADAM17 maturation and activity." (PMID 42094572, 2026). "As TNF-α is cardiotoxic and can induce cardiac dysfunction, and production of TNF-α by transgenic cardiomyocytes was sufficient to cause severe heart disease, we hypothesized that ADAM17 may upregulate TRAF3 expression through TNF-α." (PMID 39406701, 2024). "Studies have shown that ADAM17 and MT-MMP1 expression is up-regulated in cardiomyocytes and PBMCs in patients with heart disease." (PMID 23741311, 2013).
infectious disease (3 papers, 2016 to 2024). A disorder directly resulting from the presence and activity of a microbial, viral, or parasitic agent in humans. "In summary, these data suggest that ADAM17 plasma levels increase in response to malaria infection similarly to that of other infectious diseases and that the association between Ang2 levels and var gene transcript levels, although weak, is specific for EPCR-binding PfEMP1s." (PMID 27784899, 2016). "ADAM10 and ADAM17 as ubiquitously expressed proteases seem to play a central function in infectious diseases." (PMID 33392273, 2020). "However, the ADAM17 plasma levels were similar between children with UM, SM, and other infectious diseases." (PMID 27784899, 2016). "In this study, we show that plasma levels of ADAM17 are increased in Tanzanian children hospitalized with a malaria infection compared with asymptomatic children but similar to children hospitalized with other infectious diseases." (PMID 27784899, 2016). "Hence, ADAM17 might be crucial in the immunopathogenesis of several inflammatory disorders and infectious diseases, especially those that depend on TNF signaling and a balanced immune response for protective immunity." (PMID 38881671, 2024).
neurological disorders (3 papers, 2016 to 2025). "These ADAM17 conditional knockout models should be quite useful for studies focusing on ADAM17-related neurological diseases and neurogenic cardiovascular disorders." (PMID 27803674, 2016). "Although women with PCOS may not have increased susceptibility to SARS-CoV-2 infection in the brain based on viral entry protein expression, it is possible to speculate that decreased Adam17 expression in the brain could impact the neurological disorders observed in PCOS." (PMID 33922918, 2021).
retinopathy (3 papers, 2021 to 2025). "Similarly, the EGFR inhibitor erlotinib reduced pathological neovascularization in an oxygen-induced retinopathy (OIR) mouse model by inhibiting ADAM17 and EGFR." (PMID 40391004, 2025). "However, the spatial co-distribution patterns of GNAZ, ADAM17, and CLDN5 in endothelial cells partially confirmed the susceptibility of retinal endothelial cells to blue light as well as the role of retinal endothelial cells in blue-light-mediated retinopathy." (PMID 37095509, 2023). "Thus, ADAM17 may serve as a potential therapeutic target for retinopathy." (PMID 33422125, 2021).
kidney (2 papers, 2021 to 2025). "Furthermore, inhibition of ADAM17 activity improves both cholestatic liver injury and associated sickness behavior development, suggesting that ADAM17 inhibition may represent a novel therapeutic approach for treating patients with PBC/PSC." (PMID 35095853, 2021). "Conversely, ADAM17 was suggested to be an upstream mediator of NADPH oxidase in the diabetic kidney." (PMID 39859443, 2025).
gynecological disease (1 paper, 2021). "This is the first time detecting elevated ADAM17 levels in the context of malignant gynecological disease in serum." (PMID 34771725, 2021).
head and neck tumors (1 paper, 2014). "ADAM17 is a major sheddase responsible for EGFR signaling, which is a widely studied oncogene in head and neck tumors and an potential therapeutic target for OSCC treatment." (PMID 24495306, 2014).
inflammatory myopathies (1 paper, 2025). "According to a clinical study, serum ADAM17 expression was noteworthy higher in patients with inflammatory myopathies than in healthy individuals." (PMID 40224489, 2025).
ADAM17 also shares sentences with these, for which no sentence is quoted: breast tumors (4 papers); dilated cardiomyopathy (4); infertile (4); colorectal adenocarcinoma (3); meningitis (3); multiple sclerosis (3); pneumonia (3); steatosis (3); Acute Alcoholic Hepatitis (2); acute myeloid leukaemia (2); acute myocardial infarction (2); adenocarcinoma (2); allergies (2); autism spectrum disorder (2); bullous pemphigoid (2); chronic gastritis (2); clear cell renal carcinoma (2); connective tissue diseases (2); endothelial dysfunction (2); hepatic (2); leiomyoma (2); leukemia (2); myeloproliferative disease (2); non-alcoholic fatty liver disease (2); Pan (2); polycystic kidney disease (2); pulmonary hypertension (2); serous ovarian cancer (2); skin infection (2); acne (1).
A further 106 diseases each share a sentence with ADAM17 in 1 paper.